DEFB130B (defensin beta 130B)
Description:
Antimicrobial host-defense peptide. Has an antiplasmodial activity.
Tractability: Antibody: UniProt places it where antibodies can reach, with high confidence; UniProt predicts a signal peptide or a membrane-spanning region; its Gene Ontology location is reachable by antibodies, with medium confidence.
Gene: Protein-coding gene on chromosome 8 (12,064,389 to 12,071,747, reverse strand). Ensembl gene ENSG00000233050.
Subcellular location: Secreted
Pathways (Reactome):
Immune System: Beta defensins; Defensins
Gene Ontology:
Molecular function: CCR6 chemokine receptor binding; chemoattractant activity
Biological process: cell chemotaxis; defense response to bacterium; defense response; positive chemotaxis
Cellular component: extracellular region
Homologues: Orthologues: chimpanzee DEFB130 (100% identical), macaque DEFB130B (94% identical), dog CBD130 (75% identical), rat Defb41 (66% identical), mouse Defb47 (62% identical). Paralogues in human: DEFB130A (100% identical), DEFB109B (43% identical), DEFB109C (43% identical), DEFB109D (42% identical), DEFB4A (20% identical), DEFB4B (20% identical).